SFRP1 (secreted frizzled related protein 1)
Diseases named in the same sentence as SFRP1 in open-access papers (continued):
Sharing a sentence is not in itself a finding about the gene and the disease.
adenoma (continued). "Another DNA methylation study specifically evaluated methylation in four genes (SFRP1, SFRP2, SDC2 and PRIMA1), with an AUC of 0.93 for the multi-marker panel for detecting adenoma." (PMID 34503217, 2021). "DNA was available for eight such adenomas, and 3/8, 4/8, 6/8, and 2/8 revealed hypermethylation of IGF2, NEUROG1, SFRP1, and SFRP2, respectively." (PMID 26203307, 2015). "A set of transcripts (18 genes including MAL, SFRP1, SULT1A1, PRIMA1, PTGDR) showed decreasing expression (p < 0.01) in the biopsy samples along the adenoma-carcinoma sequence." (PMID 26482433, 2015). "The results of our studies however support sFRP1 suppression being an early event in tumourigenesis, as it occurs even in FAP adenomas of 3 mm or less." (PMID 20628379, 2010). "Analysis of transcriptome was performed for nine USP8-mutant and six USP8-WT adenomas and revealed the that the bidirectional dysregulation of Wnt signaling, including both the agonist RSPO2 and antagonist SFRP1, in the USP8-mutant corticotropinomas was downregulated." (PMID 39684597, 2024). "To determine whether hypermethylation of sFRP1 occurs in the large bowel mucosa and adenomas in FAP, we measured the methylation status of seven CpG sites close to the transcription start site of sFRP1." (PMID 20628379, 2010). "There was no apparent staining for sFRP1 in five of the adenomas and a further five adenomas showed only mild staining (up to 10% of the tumour cells stained)." (PMID 16523202, 2006). "We discovered widespread hypermethylation of the Wnt antagonists SFRP1, SFRP2, SFRP5, DKK2, WIF1 and SOX17 in the transition from normal to adenoma with only the Wnt antagonists SFRP1, SFRP2, DKK2 and WIF1 showing further significant increase in methylation from adenoma to carcinoma." (PMID 25432628, 2014). "In sporadic adenomas the down-regulation of sFRP1 correlates directly with an up-regulation of NKD1, but this is not always the case in the FAP adenomas." (PMID 20628379, 2010).
bladder cancer (16 papers, 2007 to 2026). "They discovered that SFRP1 methylation suppresses the gene expression and was associated with the pathogenesis of bladder cancer via the Wnt signaling pathway." (PMID 32074995, 2020). "The same group however found that 38% of bladder cancer samples showed loss of sFRP1 expression at the mRNA level whereas at the protein level loss or strong reduction of sFRP1 was observed in 66% of samples." (PMID 22325146, 2012). "Cross-WGCNA and Lasso regression identified SFRP1 and CAPG as key serum proteins linked to bladder cancer and heart failure." (PMID 41701798, 2026). "For instance, it has been reported that SFRP1 methylation inhibits its expression and contributes to the pathogenesis of bladder cancer through the Wnt signaling pathway." (PMID 39729237, 2025). "In another study, the methylation of the SFRP1 gene in bladder cancer tissues occurred more frequently than its adjacent normal tissues." (PMID 32074995, 2020). "MiR-1-3p suppressed proliferation, invasion and migration of bladder cancer cells by up-regulating SFRP1 expression." (PMID 31636323, 2019). "miR-1 inhibited proliferation, invasion and migration of bladder cancer cells by up-regulating SFRP1 expression." (PMID 29581534, 2018). "Moreover, Shang and colleagues demonstrated that miR-1-3p suppresses the invasion and migration of bladder cancer by up-regulating SFRP1 expression." (PMID 30185212, 2018). "However, SFRP1 localization is predominately cytoplasmic perinuclear in Biliary tract and bladder cancers." (PMID 25719802, 2015). "In line with that, family members of SFRP genes such as SFRP1 are thought to act as tumor suppressors and expression of SFRP1 has been shown to be downregulated in many human cancer types like colorectal, breast, bladder cancer and medulloblastoma." (PMID 25036590, 2014). "Intriguingly, the violin plots showed that both the mRNA levels of SFRP1 and SFRP2 significantly increase with the progression of bladder cancer (from stage II to stage IV)." (PMID 35372028, 2022). "Interestingly, the violin plots showed that both the mRNA levels of SFRP1 and SFRP2 significantly increase with the progression of bladder cancer (from stage II to stage IV)." (PMID 35372028, 2022). "Our study suggested that SFRP1 localization in BTC is predominately cytoplasmic perinuclear, consistent with a previous study of bladder cancer; however, the localization appears uniformly cytoplasmic in immunohistochemical staining of several other tissues in other studies." (PMID 24594839, 2014). "However, we observed that both the SFRP1 and SFRP2 mRNA levels are not inversely correlated with their methylation status using the TCGA bladder cancer database (n = 413)." (PMID 35372028, 2022).
Obesity (16 papers, 2013 to 2024). Accumulation of substantial excess body fat. "SFRP1 deficiency can increase fat weight and adipocyte size, and was regulated during adipogenesis and obesity itself." (PMID 37628891, 2023). "Loss of Sfrp1 aggravates weight gain, glucose homeostasis, and inflammation in mice with diet-induced obesity." (PMID 35159307, 2022). "Given the role Wnt/β-catenin plays in cellular proliferation, mice were injected with BrdU to evaluate the effect of Sfrp1 loss and diet induced obesity (DIO) on proliferation." (PMID 24885183, 2014). "Mice deficient in Sfrp1 show enhanced mammary gland inflammation in response to diet induced obesity (DIO)." (PMID 24885183, 2014). "Here we report that loss of Sfrp1 exacerbates weight gain, glucose homeostasis and inflammation in mice in response to diet induced obesity (DIO)." (PMID 24339864, 2013). "Meanwhile, SFRP5 deficiency resisted to diet induced obesity by stimulating mitochondrial oxidation activity and increasing SFRP1 compensation, which is mediated in part by peroxisome proliferator-activated receptor gamma coactivator 1 alpha and mitochondrial transcription factor A." (PMID 34489867, 2021). "Furthermore, sFRP-1 promotion of adipocyte differentiation was associated with physiological conditions, such as obesity." (PMID 25760577, 2015). "Considering that we observed significant Sfrp1 dependent changes in the gluconeogenic transcripts in the liver, and non-alcoholic fatty liver disease is tightly associated with obesity and hyperglycemia, we chose to examine the effects of a HFD in the livers of these mice." (PMID 24339864, 2013). "Together with the notion that obesity is associated with cancer risk, due in part to inflammation, and detection of increased macrophage infiltration in the gonadal fat pad from Sfrp1-/- mice fed a HFD mice, we investigated the inflammatory state of the mammary fat pad." (PMID 24339864, 2013). "The expression of Sfrp1 is critical for maintaining proper mammary gland development and considering that the deleterious effects of Sfrp1 depletion are exacerbated in response to DIO, loss of Sfrp1 in the context of obesity may be a critical event in cancer initiation." (PMID 24885183, 2014). "We measured a murine M2 marker (Arg1) in mice with a targeted deletion of Sfrp1 during different stages of mammary gland development including puberty, pregnancy, and lactation, as well as in response to obesity." (PMID 38554160, 2024). "Secreted frizzled-related protein 1, an inhibitor of Wnt/β-catenin signaling, has been reported to be increased in mild obesity but falls in morbid obesity, resulting in increased marrow adipose." (PMID 37629193, 2023). "Secreted frizzled-related protein 1, an inhibitor of Wnt/β-catenin signaling, peaked in mild obesity but fell in morbid obesity, which resulted in adipose changes and metabolic changes." (PMID 37629193, 2023). "SFRP1 increases in response to initial weight gain and decreases under conditions of extreme obesity in both humans and animals." (PMID 34489867, 2021). "sFRP-1 has been shown to be increased in mild obesity, leading to increased adipocyte formation, but interestingly is reduced in severe obesity, possibly to limit further adipocyte formation." (PMID 32953088, 2020). "A higher expression of sFRP-1 in mild obesity and with a gradual fall of sFRP-1 in morbidly obese individuals was reported." (PMID 32218328, 2020). "In SAT, sFRP-1 was decreased and sFRP-2 increased in obesity and accordingly, sFRP-1 negatively, while sFRP-2 positively associated with insulin resistance." (PMID 32218328, 2020). "We also discovered a novel sub-GWAS locus in SFRP1, which has already been functionally tested in mice and humans to regulate a few individual components of MetS, including obesity and glucose metabolism." (PMID 31366177, 2019). "Overexpression of sFRP-1 often related to obesity or fat accumulation inhibiting in vitro osteoblast proliferation through Wnt-β-catenin pathway." (PMID 27338453, 2016).
Obesity (continued). "On the other hand, there is limited evidence to support a role for endogenous SFRP1 in the physiological and/or pathological development of human obesity and the metabolic syndrome." (PMID 25922847, 2015). "Our data indicate that the expression of Sfrp1 is a critical factor required for maintaining appropriate cellular homeostasis in response to the onset of obesity." (PMID 24885183, 2014). "Future studies are aimed at elucidating the molecular mechanisms by which obesity and Sfrp1 downregulation affect tumorigenesis." (PMID 24885183, 2014). "The increased macrophage infiltration and pro-inflammatory cytokine expression observed in Sfrp1-/- mice was expected based on the link between obesity and inflammation." (PMID 24339864, 2013). "Considering the involvement of SFRP1 in adipogenesis and inflammation, we sought to determine the effects of diet induced obesity (DIO) in the Sfrp1-/- mouse model." (PMID 24339864, 2013). "Increased obesity has been shown to increase pro-inflammatory cytokine production and macrophage infiltration and studies have shown the involvement of SFRP1 and Wnt5a in the inflammatory response." (PMID 24339864, 2013). "Since it has previously been shown that Sfrp1 levels are reduced in the adipose tissue of severely obese mice and humans, we chose to evaluate the effects of diet-induced obesity (DIO) in Sfrp1-/- mice." (PMID 24339864, 2013). "These novel findings suggest that SFRP1 is a key regulatory factor that modulates cellular responses to obesity." (PMID 24339864, 2013). "Next, we chose to look at how Arg1 mRNA was impacted in Sfrp1−/− mice fed a high fat diet (HFD) and our findings reveal that the expression of the Arg1 is also significantly elevated in response to diet-induced obesity (DIO) in the mammary gland of Sfrp1−/− mice." (PMID 38554160, 2024). "SFRP1 was upregulated in the early stages of obesity, thereby promoting adipose tissue expansion." (PMID 37628891, 2023). "Thus, in the context of obesity, Sfrp1 expression is especially important in preventing aberrant Wnt signaling." (PMID 24885183, 2014). "Thus, it is hypothesized that fat accumulation and obesity increase expression of sFRP-1, which blocks the Wnt-β-catenin signaling pathway, thereby enhancing adipocyte differentiation through elevation of C/EBPα and PPAR-γ while suppressing osteoblast formation via downregulation of Runx2." (PMID 27338453, 2016). "The expression of a Wnt antagonist, secreted frizzled related protein 1 (SFRP1), is increased in response to initial weight gain, then levels are reduced under conditions of extreme obesity in both humans and animals." (PMID 24339864, 2013). "In obesity it has been observed that mRNA levels of SFRP1-4, but not SFRP5, were altered; finding that SFRP1, SFRP2 and SFRP4 are adipokines and their expressions correlated with insulin sensitivity." (PMID 25922847, 2015). "The PPARγ2 and SFRP1 expressions as two positives and WNT10B as a negative regulator gene of adipogenesis were evaluated in the scWAT of the individuals with different classes of obesity." (PMID 37219669, 2023).
hepatocellular carcinoma (15 papers, 2007 to 2025). A malignant tumor that arises from hepatocytes. "In 30–40% of human hepatocellular carcinomas (HCCs), activation of the pathway results from β−catenin and axin mutations or epigenetic silencing of SFRP1." (PMID 18382662, 2008). "NE activates hematopoietic stem cells and causes them to secrete sFRP1, and sFRP1 collaborates with the Wnt16/B-catenin positive feedback loop to promote hepatocellular carcinoma (HCC) progression." (PMID 34988010, 2021). "Several studies report that low expression level of SFRP1 is correlated with a poor prognosis in cholangiocarcinoma, lung, breast as well as hepatocellular carcinoma subjects." (PMID 37547756, 2023). "HCV infection promotes epigenetic inactivation of SFRP1, which is helpful for hepatocellular carcinoma." (PMID 34336665, 2021). "Further, expression of SFRP1 (secreted frizzled‐related protein) is decreased and may play an important role in the development of hepatocellular carcinoma." (PMID 32311840, 2020). "Additionally, two further studies indicated that frequent aberrant methylation of SFRPs occurs in hepatocellular carcinoma, and that restoration of SFRP1 attenuates Wnt signaling, decreases the abnormal accumulation of β-catenin in the nucleus, and suppresses cell growth." (PMID 26394929, 2015). "The levels of SFRP1, SFRP2, and SFRP5 methylation were also reported up-regulated in hepatocellular carcinoma tissues." (PMID 34205081, 2021). "Studies with mouse tumor models of hepatocellular carcinoma (HCC) have shown that administration of WNT inhibitors (WIF-1, sFRP1) reduces the density of tumor vasculature, endothelial progenitor migration, and expression of pro-angiogenesis factors." (PMID 29081735, 2017). "Similarly, the recruitment of DNMT1 and DNMT3a to the promoters of the secreted frizzled-related protein SFRP1 and SFRP5 is facilitated by HBx, leading to their downregulation in hepatoma cells and HCC patients." (PMID 33923385, 2021). "Secreted frizzled related proteins (SFRP1, SFRP2, SFRP3), which are Frizzled competitors for Wnt, are silenced by promoter hypermethylation in different cancers, including hepatocellular carcinoma (HCC), lung adenocarcinoma, oesophageal squamous cell carcinoma (ESCC) and CRC." (PMID 28931650, 2017).
osteoporosis (15 papers, 2016 to 2025). A condition of reduced bone mass, with decreased cortical thickness and a decrease in the number and size of the trabeculae of cancellous bone (but normal chemical composition), resulting in increased fracture incidence. "Within this context, upregulated levels of sFRP1 are also associated with different metabolic bone disorders including osteoporosis, mainly because of Wnt/Beta-catenin inhibition." (PMID 32424558, 2020). "miR-1-3p can reduce the expression of SFRP1, thus promoting bone formation and mineral density and preventing osteoporosis." (PMID 37782397, 2024). "To illustrate the complicated regulation of Sfrp1 by different miRNAs in osteoporosis, we focused on Wnt–β‐catenin signalling." (PMID 38748896, 2024). "It has been suggested that the anabolic effect of the parathyroid hormone (PTH), an FDA approved osteo-anabolic drug commonly used for osteoporosis treatment, requires Sfrp1 downregulation to stimulate Wnt signaling and osteoblastogenesis." (PMID 34452242, 2021). "That decrease of bone mass was associated with the increasing expression of miR-542-3p, involved in the downregulation of osteoblast differentiation by targeting SFRP1 in rats after ovariectomy-related osteoporosis." (PMID 31947616, 2020). "In this study, we first established an ovariectomized (OVX) rat model to simulate postmenopausal osteoporosis and found significant changes in miR‐542‐3p and sFRP1 expression by RNA sequencing and qRT‐PCR." (PMID 29319176, 2018). "In this study, we found that sFRP1 and miR‐542‐3p were negatively correlated in postmenopausal osteoporosis patients." (PMID 29319176, 2018). "Thus, further investigations on the miRNAs involved in the inflammatory responses and the regulation of Sfrp1 expression during osteogenic differentiation of BMSCs are warranted to fully elucidate the roles of Sfp1 in osteoporosis development." (PMID 38748896, 2024). "This study demonstrated that TNF‐α regulates the miR‐27a‐3p–Sfrp1 axis in osteoporosis." (PMID 38748896, 2024). "Our results demonstrated that the WTAP/YTHDC1/miR-181a and miR-181c/SFRP1 axis regulated the differentiation fate of BMSCs, suggesting that it might be a potential therapeutic target for osteoporosis." (PMID 36650131, 2023). "Our research revealed that WTAP could promote osteogenic differentiation and inhibit adipogenic differentiation of BMSCs through the YTHDC1/ miR-181a and miR-181c /SFRP1 axes, which could be of significance in developing therapeutic targets for osteoporosis." (PMID 36650131, 2023). "Moreover, in a recent study involving Chinese patients with osteoporosis, miR-1-3p expression was reported to be significantly downregulated and SFRP1 expression was upregulated with reduced bone formation and bone mass." (PMID 34407854, 2021). "In summary, our findings identified that lncRNA SNHG1 regulated by SP1 play a promoting role in osteoporosis development that suppressing osteogenic differentiation and angiogenesis but facilitating osteoclast differentiation by modulating SFRP1-mediated Wnt signaling through sponging miR-181c-5p." (PMID 34732133, 2021). "Understanding the cross-regulation between SFRP1 and estrogen sensitivity could allow us to better understand both breast tumorigenesis and menopause-related osteoporosis." (PMID 31947616, 2020). "In the present study, we indicate that miR‐542‐3p is a novel miRNA that could ameliorate ovariectomy‐induced osteoporosis in rats by directly targeting sFRP1." (PMID 29319176, 2018). "Thus, the development of inhibitors against SFRP1 is a viable method of stimulating bone formation in metabolic bone diseases, osteoporosis and aging." (PMID 29319176, 2018). "Thus, the development of Sfrp-1 silencing based therapies could be a viable strategy for enhancing bone formation when diminished bone growth is present such as primary osteoporosis and glucocorticoid induced osteoporosis." (PMID 36309688, 2022).
osteoporosis (continued). "Thus, SFRP1 could be the basis of an effective strategy for preventing osteoporosis." (PMID 39606935, 2025). "The administration of the developed nanoparticles containing an encapsulated GapmeR for silencing SFRP1 and decorated with a specific MSC aptamer proved to be a successful therapy in the treatment of osteoporosis." (PMID 36309688, 2022). "Secreted frizzled‐related protein‐1 (SFRP1) is a negative regulatory molecule of the WNT signaling pathway and serves as a therapeutic target for bone formation in osteoporosis." (PMID 29319176, 2018). "In addition, there was a significant negative correlation between miR‐542‐3p and sFRP1 mRNA levels in postmenopausal women with osteoporosis." (PMID 29319176, 2018). "Understanding of the molecular mechanisms involved in promoting bone density has been important to the development of multiple drug therapies for osteoporosis, such as the capthepsin K inhibitors Odanacatib and Balicatib, anti-SOST antibodies, anti-Dkk1 antibodies, and GSK3β and Sfrp1 inhibitors." (PMID 27483347, 2016).